TNF (tumor necrosis factor)
Diseases named in the same sentence as TNF in open-access papers (continued):
Sharing a sentence is not in itself a finding about the gene and the disease.
infection (continued). "A study conducted on primary human brain endothelial cells revealed that infection with recombinant, wt NiV-Malaysia induces high levels of inflammatory cytokines such as IL-6, TNF-α, IL-8, eotaxin, MCP-1, MIP-1β and IP-10." (PMID 39466030, 2024). "While upregulation of the TNF-a gene was significant in both ileal and rectal monolayers at 4 h post infection with EHEC (p < 0.05), that of IL-8 was significant only in rectal monolayers (ileum: p = 0.09 and rectum: p < 0.01)." (PMID 38732126, 2024). "When LysM Cre+Ifnarflox/flox mice were intraperitoneally infected, anti-TNF-α Ab treatment protected all mice from lethal infection with DV1-5P7Sp." (PMID 38550855, 2024). "Compared with WT/Vector strain, infection with the WT/PrrH and the ΔprrH/PrrH strains increased the expression of tumor necrosis factor-α (TNF-α) and interleukin-1β (IL-1β)." (PMID 38289930, 2024). "What is more, aged mice treated with anti‐TNF antibody prior to infection experienced less severe disease, evidenced by the decreased bacterial burden in the blood, spleen, and heart compared to mice treated with anti‐HRP isotype control antibody." (PMID 38459711, 2024). "According to Grimble39, it is considered beneficial the presence of cytokines (e.g. IL-1β and TNF-α) in adequate concentrations during an inflammatory response to infection." (PMID 38789563, 2024). "The UL26 tegument protein, which is important for high titer replication, restricts the expression of cytokine signaling genes during infection and antagonizes TNFα-induced NFκB activation." (PMID 38768227, 2024). "Infection or CNS damage can activate microglia, and activated microglia release IL-6, IL-1β, and TNF-α." (PMID 39661619, 2024). "Based on IL-6 and TNF-α secretion, the data suggest that compared to infection with RB51, the inflammatory response induced by S2308 in RAW264.7 cells is more delayed." (PMID 38464511, 2024). "Though in limited amounts, TNF-α production by NK cells was only evident in Salmonella-single infection both in blood and spleen." (PMID 38918457, 2024). "Tumor necrosis factor (TNF), a prototypical proinflammatory cytokine, has been implicated in generating protective immunity to various infections." (PMID 39044282, 2024). "An essential role in the response to infection injuries is played by tumor necrosis factor-α, which is a pro-inflammatory cytokine produced by most macrophages, it also plays a role in angiogenesis, apoptosis and other physiological processes." (PMID 38920850, 2024). "All infections caused enrichment with inflammatory response signaling pathways, fibrogenesis and cell proliferation, and IL2–STAT5, TNF–NF-κB, TGF-β, Hippo, MAPK, and PI3K–Akt signaling pathways." (PMID 39652576, 2024). "Among pro-inflammatory cytokines, tumor necrosis factor (TNF), interleukin (IL)-6, and IL-1β are produced early during infection." (PMID 39844838, 2024). "TNF‐α and IL‐6 are pro‐inflammatory cytokines that play pivotal roles in the immune response and are often used as markers of inflammation and infection." (PMID 39422648, 2024). "We have also reported robust TNF production by G-MDSCs, PMNs, macrophages, and microglia in vitro as well as in vivo during craniotomy infection." (PMID 39044282, 2024). "First, we determined the quantity of production for IL-1β, IL-6, and TNF-α in the lung as the primary site of infection." (PMID 38646937, 2024). "A statistically significant increase in the TNF-α mRNA levels was observed on the 20th and 30th post-infection days compared to the 10th post-infection day (p < 0.05)." (PMID 39766497, 2024). "Studies have shown a positive regulation of the gene expression of pro-inflammatory cytokines (IL-1β, TNF-α, and IL-6) in human macrophages after infection with L. amazonensis and L. major." (PMID 39199338, 2024).
infection (continued). "Consistently, we observed significantly higher IL-6 levels in primary Mettl3 cKO BMDM compared to Mettl3 WT BMDM following infection with P. multocida and S. aureus for 0–12 h, and M. pneumoniae for 0–24 h, as well as TNF-α." (PMID 38182816, 2024). "Cytometric bead array (CBA) analysis revealed that the expression of TNF in the serum of mice increased concomitantly with the prolongation of infection duration." (PMID 38805557, 2024). "We found that infection of neonatal mouse cardiomyocytes with both T. cruzi isolates with different virulence degrees, followed by stimulation with TNF-α + IFN-γ, led to a significant decrease in NOS2 expression, which was similar in magnitude." (PMID 39452749, 2024). "It is a notable finding that the highest levels of TNF-α mRNA were observed on the 20th and 30th days following infection." (PMID 39766497, 2024). "TNFα increased in the 2-week post-infection groups, in the mice treated with Nocardia, and also in the mice receiving the double treatment." (PMID 38542396, 2024). "Enteric glia are specialized cells that support the immune system of the gastrointestinal tract and are the major producers of TNFα upon infection." (PMID 38542396, 2024). "Infection of THP-1 cells with A.baumannii significantly induced cellular production of TNF-α and IL-6, and the positive control PMB significantly inhibited the production of inflammatory factors." (PMID 38956179, 2024). "Resistant to infection as the wild type, and therefore NsTNF was considered functionally redundant to TNF." (PMID 39949719, 2024). "Of the genes within these intersecting pathways, 120 were significantly induced in both ΔUL26 infection and TNFα-treated PIAS1 KO cells relative to their respective control conditions." (PMID 38768227, 2024). "Considerable inflammatory cells infiltrating in the endometrium, with high levels of pro-inflammatory cytokines of interleukin (IL)-6, IL-1β and tumor necrosis factor-α mRNA after infection." (PMID 39545261, 2024). "The gene expression levels of four cytokines; TNF-α, IL-6, IL-1β, and IL-8 were tested in the cell lines after infection." (PMID 39427065, 2024). "Studies with different infectious agents have demonstrated increased levels of inflammatory cytokines, such as IFN-γ and TNF-α, after infection is established." (PMID 39066175, 2024). "Here, we show that TNF is critical for stimulating chemokine production and leukocyte recruitment during acute craniotomy infection since both were significantly reduced in TNF KO mice." (PMID 39044282, 2024). "Pro-inflammatory cytokines such as TNF-α and IL-1β play crucial roles in immune responses, serving as vital mediators that communicate tissue distress due to infection or injury." (PMID 39452085, 2024). "Dormant infections displayed an upregulation of inflammatory pathways involved in the activation of TNF and IL-17 signaling (FDR < 0.01) when compared to uninfected (FDR < 0.01 for both) and infected (FDR < 0.01 or both) joint replacements." (PMID 39563367, 2024). "TNF-α recruits inflammatory cells, including macrophages and T cells, to the site of infection, thus promoting increased macrophage phagocytic activity, which leads to granuloma formation and maintenance." (PMID 38612420, 2024). "The same did not occur with the TNF-α-producing CD4+ T lymphocytes; even though TNF-α is necessary to resolve the infection, this cytokine is related to liver damage." (PMID 38690280, 2024). "In previous studies, a single application or mixture of probiotics has shown the reduction of proinflammatory cytokines including IFN-γ IL1B, IL2, IL8, and TNF-α in various animal species and cell lines after pathogen-induced infection." (PMID 38561808, 2024). "Upon infection with Mycobacterium tuberculosis (M.tb), T2D-HAMs had more M.tb growth and produced more TNF." (PMID 39649174, 2024).
infection (continued). "With regards to expression differences of anti-inflammatory (IL-10) and pro-inflammatory (IFN-γ and TNF-α) cytokines between 24 and 48 hr post-infection, significant differences were observed in the results in response to some sensitive and resistant strains." (PMID 38800030, 2024). "This was further confirmed in a lethal systemic mouse infection model in which MEndoB significantly reduced S. aureus loads and tumor necrosis factor alpha levels in blood in a dose-dependent manner, which led to increased survival of the animals." (PMID 38275913, 2024). "To assess if cytokine-mediated or cytolytic effector functions play a dominant role in NrHV clearance, we analyzed the course of infection in TNF-α-/-, IFNγR-/- and Perforin-/- mice." (PMID 39392861, 2024). "Eight hours after M. gallisepticum infection in chicken primary alveolar type II epithelial cells, large amounts of TNF-α and IL-6 were produced and inflammation was suppressed 24 h after infection." (PMID 38474071, 2024). "The TNF-α concentrations were higher following RVC G3P infection in the piglets colonized with HBGA+ vs. HBGA− bacteria (p < 0.05)." (PMID 38793542, 2024). "The TNF-α mRNA levels were observed to increase by 4.8 (p < 0.05), 12.4 (p < 0.001) and 12.1 (p < 0.001)-fold on average at days 10, 20 and 30 post-infection with T. gondii, respectively, in comparison to the healthy control groups." (PMID 39766497, 2024). "In conclusion, we demonstrate a role for TNF in leukocyte recruitment to the site of craniotomy infection by its ability to promote chemokine production." (PMID 39044282, 2024). "This makes craniotomy infection unique from other S. aureus models where TNF is critical for bacterial containment." (PMID 39044282, 2024). "Instead, this suggests that other factors unique to the craniotomy infection microenvironment influence the TNF-independent phenotypes reported here." (PMID 39044282, 2024). "Both mouse strains have higher levels of TNFα, IL-6, IL-17A, and IL-17F in whole stomach homogenates after infection, illustrating that the type 3 model of gastric mucosal inflammation and C. albicans pathogenesis is applicable in both C57BL/6 and BALB/c mice." (PMID 39347572, 2024). "An increase of both cytokines was observed for both infection doses compared to the control (IL-10: 7.75 pg/ml; TNF: 22.89 pg/ml)." (PMID 38979428, 2024). "Trametinib significantly inhibited TNFα release by both infected and uninfected cells at both 100 nM and 1 μM with the reduction apparent at early (6 hpi) and later points of infection (24 hpi)." (PMID 38916198, 2024). "Although controlled and local TNF/TNFRI activation aids infection resolution and tissue repair, excess TNF can be harmful." (PMID 39335653, 2024). "PM10 exposure followed by infection significantly increased the protein levels of TNF-α (A), IL-1β (B), and CXCL2 (C), and decreased GPX4 (D) and Nrf2 (E) (p < 0.001 for each)." (PMID 38928968, 2024). "The studies showed that early in infection, when alveolar macrophages interact with fungal cells, essential pro-inflammatory cytokines were produced: IL-12, TNF, IL-1, IFN-γ and GM-CSF." (PMID 38198478, 2024). "Exposure to PM10 followed by infection significantly elevated relative mRNA levels for TNF-α, IL-1β, CXCL2, TLR4, IL-6, COX2, and iNOS when compared to control air (p < 0.001 for all)." (PMID 38928968, 2024). "Further, our CBA analyses highlighted a very low renal induction of IL-10 in comparison to the robust induction of IFN-γ and TNF-α in mice after seven days of infection." (PMID 38787228, 2024). "Specifically, wild-type PRRSV-2 increased activation of NF-κB and enhanced induction of IL-6, IL-8, and TNF-α in coinfected cells compared to single infection with S. suis." (PMID 38547254, 2024). "MNKs have been implicated in mediating the production of pro-inflammatory cytokines, such as TNF-α, IL-6, and IL-1β, during infection and inflammation." (PMID 38980024, 2024).
infection (continued). "An early production of TNF-α was detected in the mouse lungs, followed by lung colonization at 12 h and dissemination to the bloodstream at 18 h post infection." (PMID 38559342, 2024). "Epithelial cells are early responders to infection and induce downstream effectors such as IL-6, IL-8, TNF-α, IFN-γ, and nitric oxide (14, –, 16)." (PMID 38407132, 2024). "Our previous study identified a transcriptional footprint of TNF signaling during craniotomy infection, which was particularly elevated in granulocytes." (PMID 39044282, 2024). "In this study, the levels of IL-1β, IL-6, IL-10, and TNF-α in the sera of mice were measured three days after infection with Lm928, ΔEIIB, and CΔEIIB." (PMID 39057985, 2024). "After 6 hours of infection, we measured the expression levels of the proinflammatory cytokines IL-6 and TNF-α." (PMID 38912723, 2024). "The nisin treatment groups had lower cytokine expression levels (TNF-α and IL-6) in the oral cavity and uterus compared to the infection groups." (PMID 39203489, 2024). "CD4 T cells were found to produce multiple proinflammatory cytokines such as IFN gamma, TNF-α, and IL-2 that provide protective effects but also induce many of the damaging effects of Mtb during active infection." (PMID 38892443, 2024). "Western Blot data for basal media samples confirmed that IL-8 was only detectable after day3 of infection, while TNFα was below the detection limit throughout." (PMID 38990812, 2024). "The mixture of various probiotics and Bifidobacterium with galactooligosaccharides and fructo-oligosaccharides has a defensive effect against infections, aggregating the production of TNF-α, IL-4, IFN-γ and TLR2 expression." (PMID 39608222, 2024). "Our investigation showed that S. suis strains of cps2, 14, and 9 induced IL-1β and TNF-α following in vitro infection of porcine blood as previously reported in human whole blood." (PMID 38317258, 2024). "In contrast to the robust response seen with LCMV, RRV-gp33 infection induced tenfold lower levels of IFNγ and TNF producing CD8+ T cells after peptide restimulation, and GrB expression was apparent in only 5% of DLN CD8+ T cells at 5 dpi." (PMID 39535221, 2024). "Further studies have shown an early reduction in inflammatory recruitment at the site of infection, likely due to the drug’s effects on pro-inflammatory cytokines and chemokines, like IL-6, TNF, and MCP-1." (PMID 39204231, 2024). "Infection with the Beta variant had little impact on the production of Interferon γ-induced protein 10/IP-10 (C-X-C motif chemokine ligand 10/CXCL-10) and tumor necrosis factor-α (TNF-α), and resulted in a significant increase in Interleukin 6 (IL-6) levels." (PMID 38568894, 2024). "Consistently, quantitative PCR analysis revealed that the mRNA expression of inflammatory cytokines, including IFN-γ, IL-6, and TNF-α, was upregulated in the lungs of MA10-infected mice, suggesting that MA10 infection caused lung injury." (PMID 38634132, 2024). "Conti and collaborators observed that, at early timepoints post-infection, Vpr confers on infected PBMCs protection from apoptosis despite the presence of TNF-α signaling, although a completely opposite outcome presented itself at later timepoints." (PMID 38543785, 2024). "Notwithstanding, the anti-TNF-α antibody aggravated bacterial burden in the established infection, impairing granuloma organization in injected mouse lung sections." (PMID 37196131, 2024). "In this study, we observed that TNF-α increased from day 10 post-infection and remained at high pathological levels, whereas IL-1β increased from day 20 to day 30 post-infection, which is a particularly intriguing finding." (PMID 39766497, 2024). "Studies have shown that CD8+ T cells can also secrete a variety of pro-inflammatory cytokines, mainly IFN-γ and TNF-α, to inhibit viral replication, and express various chemokines to recruit inflammatory cells to the site of infection." (PMID 39081314, 2024).
infection (continued). "On the contrary, we found that the ECRG4 KO mouse infection had increased expression of IL1β (P = 0.0053), IL-6 (P = 0.047) and TNFα (P = 0.024), with a trend towards increased CXCL1." (PMID 39509414, 2024). "Macrophages containing Mmm antigens are found in the lungs of infected animals and they produce the archetypal pro-inflammatory cytokine TNF upon infection in vitro." (PMID 38935768, 2024). "A strong positive expression of TNF-α was observed in the epithelial and vascular endothelial cells in the infection group." (PMID 38708351, 2024). "After 24 h of infection, both T. forsythia stimuli significantly upregulated gene expression of IL-6, TNF-α, IL-8, and MCP-1." (PMID 39035711, 2024). "PTX3, part of the long pentraxin subfamily and inducible by IL-1 or TNF, plays a role in infection defense, tissue repair, and managing inflammation in cancer." (PMID 38895120, 2024). "Concurrently, the cytokine expression profile demonstrates a gradual elevation in IL5, IL13, IFNγ, and TNF, indicating an increasingly complex immunomodulatory environment according to the infection dose." (PMID 39621794, 2024). "Our data showed that MHV-A59 infection significantly increased the proportions of TNF+, iNOS+, and IL-10+ macrophages, as well as TNF+ neutrophils, in the lungs of Smurf1−/− animals compared to wild-type animals." (PMID 39452742, 2024). "The production of TNF-α, iNOS, and IL-12 by inflammatory monocytes at the infection site has been demonstrated to be crucial in eradicating T. gondii and other bacteria such as Listeria monocytogenes." (PMID 39051675, 2024). "We have previously demonstrated that TNF contributes to age‐dependent macrophage dysfunction (ADMD) and the enhanced susceptibility of aged animals to infection." (PMID 38459711, 2024). "NF-κB, TNF-α, and Il-10 levels increased in response to infection and decreased in response to various treatments, with the highest reduction in the group treated with combined NTZ citrus Cs/Ag NPs." (PMID 39065665, 2024). "Analgesic treatment did not alter the internal cytokine levels, including IFN-γ, IL-10, IL-1β, and TNF-α, at 24 hours after infection." (PMID 39281680, 2024). "Corresponding with the increased gene expression of Il1a and Tnfa, IL-1α and TNF- protein in the airways was also significantly elevated on day 1 post infection in mice exposed to LPS before RSV infection compared to LPS only and RSV only mice." (PMID 39127259, 2024). "In an inflammatory context, resident cells, such as macrophages, release a cascade of pro-inflammatory cytokines, including IL-1β and TNF-α, which act as signaling molecules, coordinating the host’s response to injury or infection." (PMID 39409022, 2024). "S. aureus exposure did not increase the capacity of macrophages to directly kill intracellular E. coli but instead promoted IL-6, TNF, and IL-1β production by these cells, leading to enhanced recruitment of neutrophils to clear the infection." (PMID 39618498, 2024). "Mice were treated with α-IL-1α and α-TNF-α in combination (α-Duo) receiving daily i.p. injections up to day 2 post infection and weighed up to day 8 post infection." (PMID 39127259, 2024). "Another footprint of TNF action in vivo was decreased PMN and G-MDSC recruitment in all three tissue compartments of TNF KO animals, which peaked at day 14 and recovered by day 28 post-craniotomy infection." (PMID 39044282, 2024). "Significant decreases in CCL3, CCL4, and CXCL2 were observed in the galea of TNF KO mice at day 14 post-infection, corresponding to the timepoint and anatomical location where granulocyte recruitment was maximally reduced." (PMID 39044282, 2024). "In the mock treated animals, the highest frequencies of TNFα-producing CD4+ T-cells were detected at day three post-infection preceding the CD8+ T-cell response by two days." (PMID 39472590, 2024).